MYO6 (myosin VI)
Diseases named in the same sentence as MYO6 in open-access papers (continued):
Sharing a sentence is not in itself a finding about the gene and the disease.
tumor (20 papers, 2008 to 2025). "Meanwhile, myosin VI translocates from the junctions to the membrane edge at the invasive front of the cells, thus accelerating cell migration and causing tumor invasion." (PMID 27121062, 2016). "Associations between immunostaining for myosin VI and tumour class, stage, grade and histological subtype of RCC." (PMID 20074327, 2010). "Furthermore, we performed correlation analyses and found that either downregulation of miR-143/miR-145 or upregulation of MYO6 was associated with larger tumor size and more frequent metastasis in GC patients." (PMID 29022908, 2017). "Among the genes with significant differences, NAPSA, MUC1, WFDC2, and MYO6 were well correlated with Tumor_C1 and Unknow_C2 (cells with a high positive rate of tumor markers), and these two cell clusters were all cells with a high positive rate of PD-L1." (PMID 39991571, 2025). "We propose that the upregulation of MYO6 expression observed in tumor versus normal prostate tissue is due, at least in part, to downregulation of miR-145-5p." (PMID 38673886, 2024). "The expression of MYO6 mRNA was notably reinforced in tumor tissues, and the protein level of MYO6 was also notably reinforced in 6 randomly selected tumor tissues from CRC patients." (PMID 34645476, 2021). "The tumours were examined with three immunohistochemical markers: myosin VI, E-cadherin and beta-catenin." (PMID 20074327, 2010). "When tumour diameter was retained in the model, HR for cytoplasmic myosin VI was 3.5 (95% CI 1.5 to 7.9) with p = 0.003." (PMID 20074327, 2010). "The mean survival times for subjects with Fuhrman grade II cytoplasmic myosin VI immunonegative and immunopositive tumours died of RCC during follow-up were 101 (standard deviation (SD) ± 71) and 52 (SD ± 47) months, respectively." (PMID 20074327, 2010). "Noteworthy, the HR for cytoplasmic myosin VI immunostaining was increased also when tumour diameter, age or gender was retained to the model." (PMID 20074327, 2010). "So cytoplasmic myosin VI immunopositivity seems to have prognostic potential also within Fuhrman grade II tumours but not only within poorly differentiated tumours." (PMID 20074327, 2010). "A monoclonal antibody to myosin VI (MYO6) stained luminal cells with a homogeneous cytoplasmic pattern, with tumor cells showing frequent apical reinforcement." (PMID 18973659, 2008). "In addition, high expression of myosin VI (MYO6) was related to tumor proliferation and metastasis in vitro." (PMID 41262242, 2025). "Notably, LDHA, SHC1, and EPHX1 exhibited heightened expression levels in tumor tissues, while MYO6 and TLE1 displayed diminished expression compared to normal tissues." (PMID 37965333, 2023). "Furthermore, LINC01224 and MYO6 abundances were markedly higher and miR-485-5p was lower in the tumor tissues with sh-LINC01224#1 transfection." (PMID 34535152, 2021). "One-third of the tumours were immunopositive for nuclear myosin VI." (PMID 20074327, 2010). "They contribute a lot to tumor initiation and development by controlling the expression and function of tumor suppressor genes, including K-RAS, ELK1, MYO6, BCL2, ERK5 and IGF1R." (PMID 27626488, 2016). "In line with the signature prognostic value, from the STRING network analysis emerged an implication of EBF1, MYO6, and CALR in the regulation of tumor progression together with the control of B lymphocyte gene transcription, intracellular vesicle transport and protein folding." (PMID 38035116, 2023). "Silencing of UCA1 inhibited PCa cell proliferation, migration and invasion and promoted chemo-sensitivity in vitro and tumour growth in vivo.In addition, UCA1 sponges tumour-suppressive, anti-proliferative miR-143, leading to derepression of its oncogenic target, MYO6 in PCa." (PMID 35159022, 2022). "In addition, we identified MYO6 as an important common target gene of miR-143 and miR-145 and further demonstrated that the tumor-suppressive and EMT-inhibitory roles of miR-143 and miR-145 are mediated by MYO6." (PMID 29022908, 2017).
infection (6 papers, 2014 to 2025). The state of being infected such as from the introduction of a foreign agent such as serum, vaccine, antigenic substance or organism. "HeLa cells depleted of myosin VI protein expression by siRNA transfection exhibited an accumulation of cells with ubiquitin positive (+) ΔsifA Salmonella at 1, 4, and 8 hours post-infection." (PMID 26451915, 2015). "Internalised Salmonella were harvested from HeLa cells at 2, 4, or 8 hours post-infection in mock and myosin VI or TAX1BP1/NDP52/optineurin (TNO) siRNA depleted cells and the fold replication of Salmonella was measured." (PMID 26451915, 2015). "Indeed, a recent work described the essential role for both T6BP and MYOSIN VI in the late phase of autophagy for an efficient clearing of intracellular infection by Salmonella typhimurium." (PMID 28531150, 2017). "Thus, at 8 hours post-infection, the number of cells containing ubiquitin-positive Salmonella were quantitated in myosin VI or TNO depleted cells." (PMID 26451915, 2015). "While downregulation of MYO6, involved in actin-based motility, did not influence MHV infection (dark orange), our results indicate that the microtubule-associated motility proteins DYNC1H1 and DYNC2H1 are important for infection with MHV (orange)." (PMID 25375324, 2014). "Myo6 and EGFR, host factors involved in IAV entry, were detected but not enriched upon infection." (PMID 40623098, 2025).
bacterial infection (1 paper, 2016). "During pathogen infection autophagy plays a key role through clearance of the pathogen in a process known as xenophagy and NDP52 and myosin VI have been shown to promote autophagosome maturation during bacterial infection." (PMID 27147468, 2016). "Recently, Tumbarello and co-workers also demonstrated that during bacterial infection, both myosin VI and its interactor TAX1BP1 are required for xenophagy." (PMID 27147468, 2016).
MYO6 also shares sentences with these, for which no sentence is quoted: Hearing impairment (4 papers); autosomal recessive deafness (2); breast (2); colon adenocarcinoma (1); diffuse large B-cell lymphoma (1); epilepsy (1); genetic diseases (1); hearing disorder (1); hepatocellular carcinoma (1); language delay (1); lung adenocarcinoma (1); mitochondrial disease (1); myeloproliferative disorder (1); Onset (1); oral squamous cell carcinoma (1); osteosarcoma (1); Perrault syndrome (1); prostate (1); rectum adenocarcinoma (1); renal cell carcinoma (1); schizophrenia (1); squamous cell carcinoma (1); Usher syndrome (1); Waardenburg syndrome (1).